IL1B (interleukin 1 beta)
Diseases named in the same sentence as IL1B in open-access papers (continued):
Sharing a sentence is not in itself a finding about the gene and the disease.
asthma (continued). "The present data obtained in WT and IL-1β-deficient mice suggest that viral induced asthma exacerbation in part may depend on IL-1β, whereas baseline HDM-induced experimental asthma may not." (PMID 29361942, 2018). "Our data suggested that Th1-related cytokine, macrophage-derived IL-1β, was also significantly upregulated in the CVA model, and the downstream NF-κB signaling pathway was also activated, which would dramatically stimulate the release of proinflammatory cytokines to worsen asthma." (PMID 29951106, 2018). "Sputum levels of IL-1β were also significantly elevated in neutrophilic asthma, in agreement with our previous data and we extend this by showing that levels of IL-1RA, the receptor antagonist for IL-1β, was not different between the asthma phenotypes." (PMID 25616863, 2015). "Interestingly CXCL10 production induced by IFNγ or cytomix is also not inhibited by current asthma therapies such as fluticasone and/or salmeterol, whereas IL-1β- and TNF-α-induced release is markedly reduced by these agents." (PMID 24648846, 2014). "Also, several inflammatory mediators, of potential relevance to asthma, such as SOCS1, IL1B, IL13RA1 and CCL26 could be potentially affected, directly or indirectly by one or more microRNAs of this list." (PMID 25360780, 2014). "In addition, cytokines secreted by type 1 lymphocytes (Th1) and macrophages, including IL-1β, TNF-α, and IFN-γ, may be increased in asthma subjects and contribute to the inflammatory process." (PMID 19152703, 2009). "The fact that pro-inflammatory cytokines like IL-1β can alter airway contractile responses to contractile agents such as 5-HT, via interference with the intracellular MAPK signal transduction pathways, might provide a new concept for the treatment of asthma." (PMID 17407556, 2007). "The fact that IL-1β can alter airway responses to contractile agents such as 5-HT, via alteration of the intracellular MAPK signal transduction pathways, might provide a new concept for future treatment of asthma." (PMID 17407556, 2007). "In addition, CARD11+ populations among ILC3s and LPS-stimulated IL-1β+CD16+ monocytes from the PBMCs of obese individuals with asthma were significantly greater than those from obese controls or nonobese individuals with asthma." (PMID 39672814, 2024). "Moreover, a study with IL-4- and IL-13-treated macrophages stimulated with IL-33 (an asthma cellular model) induced an increase in the expression of miR-155-5p, along with an increase in inflammatory mediators (Ccl3, Ccl5, Ccl17, Ccl24, and Il1b) compared to macrophages without pretreatment." (PMID 38337625, 2024). "In this study, the expression of CXCL8 and CXCL1 in ILC3s upon IL-1β stimulation was insensitive to dexamethasone, suggesting that neutrophilic inflammation mediated by IL-1β-ILC3-CXCL8/CXCL1 axis may be involved in the development of steroid-resistant of asthma." (PMID 36949482, 2023). "Given that IL-1β production is not responsive to steroids in severe asthma, our data imply that dietary fat restriction may be an important adjunct to other therapies used in obese asthma." (PMID 29686414, 2018). "IL-1β, may not have been extensively studied in relation to exacerbations of asthma." (PMID 29361942, 2018). "Our data further show that in asthma patients, irrespective of their T2D status, MCP-1 associated positively also with IL-1RA which is an important indicator of the anti-inflammatory competency of these individuals while the IL-1β/IL-1RA balance plays a key role in asthmatic inflammation." (PMID 27709105, 2015). "A six-gene signature (CLC, CPA3, DNASE1L3, IL1B, ALPL, and CXCR2) can differentiate asthma patients from controls, discriminate inflammatory phenotypes of asthma and predict the ICS response, but this method is not currently available." (PMID 30598830, 2018).
asthma (continued). "Thus, reduction of IL-1β levels by the HBG extract could contribute to the broad range of traditional medicinal applications previously reported for Muricidae molluscs, including preparations that have been used to treat asthma, cough and reduction of respiratory phlegm." (PMID 29073178, 2017). "In non-diabetic individuals with asthma, MCP-1 levels correlated with IL-1β, IL-1RA, MDC/CCL-22, IP-10/CXCL-10, GM-CSF, FGF-2, PDGF-AA, PDGF-BB, and HbA1c." (PMID 27709105, 2015). "TNF-α- or IL-1β-induced CXCL10 release by ASMC from people with and without asthma was strongly inhibited by GC and LABA treatment in this study." (PMID 23034049, 2012). "We observed comparatively similar levels of acute inflammatory markers (e.g., – IL-1β, IL-6, TNFα) in TRPM-stimulated whole blood from children with and without asthma, which was contrary to our a priori study hypothesis." (PMID 28424616, 2017). "Furthermore, additional inflammatory cytokines such as IL-1β and TNF-α are derived primarily from macrophages (not Th1 or Th2-derived) and also play a significant role in asthma inflammation." (PMID 19152703, 2009). "While modest evidence of correlation exists for cytokines such at TNF-α, IL-1β, and IL-6, there is a notable lack of correlation evident for the IL-8 responses to endotoxin and TRPM, whether the study subjects were considered as a single group, or as sub-groups based on asthma control status." (PMID 28424616, 2017).
psoriasis (422 papers, 2010 to 2026). An autoimmune condition characterized by red, well-delineated plaques with silvery scales that are usually on the extensor surfaces and scalp. "Notwithstanding these limitations, our work provides a solid foundation for targeting the IL-1β–AMPK interaction as a viable therapeutic strategy for psoriasis and its associated metabolic comorbidities." (PMID 41508030, 2026). "contains bioactive flavonoids and alkaloids that exert anti-inflammatory and antioxidant activities, and inhibit TNF-α, IL-1β, IL-6 and NF-κB signaling pathways implicated in the pathogenesis of psoriasis." (PMID 42306466, 2026). "Estrogens suppress the production of psoriasis-related cytokines such as IL-1β and IL-23 from neutrophils and dendritic cells, respectively, and this suppression likely helps mitigate the inflammatory response associated with psoriasis." (PMID 40621451, 2025). "Group 3 innate lymphoid cells lack rearranged antigen-specific receptors, rely on the transcription factor RORγt, and respond to IL-1β and IL-23; a subset of group 3 innate lymphoid cells is associated with production of IL-17A and IL-22 in psoriasis lesions." (PMID 39114670, 2024). "In summary, our study delved into the role of autophagy in myeloid cells with a focus on macrophages and provided an insight into the pathogenic mechanism of psoriasis involving IL-1β dysregulation induced by autophagy deficiency." (PMID 38704587, 2024). "We then assessed the pathogenic mechanism focusing on immune cells producing IL-1β and IL-17 along with gene expression profiles associated with psoriasis in mouse model and public database on patients." (PMID 38704587, 2024). "Given the pivotal roles of pro-inflammatory cytokines such as IL-6, TNF-α, IL-1β, and Th17-associated cytokines, in psoriasis development, we compared their expression levels in IMQ-treated WT and CD169-DTR mice." (PMID 38891893, 2024). "This is also true for the release of cytokines like IL-17, IL-6, and IL-1β, which are closely linked to the development of psoriasis." (PMID 39296901, 2024). "IL-1β is a cytokine highly expressed in psoriasis samples, and two genetic variants, rs16944 and rs2853550, were proven to be associated with late initiation of the disease and a slower progression." (PMID 38793117, 2024). "IL-23 has been established as a key player in the pathogenesis of psoriasis by promoting the generation of pathogenic Th17 and IL-17-producing γδ T cells, which can be synergized upon combination with IL-1β." (PMID 38704587, 2024). "Recent study highlights the critical role of IL-1β in the induction and activation of pathogenic Th17 and IL-17-producing γδ T cells, contributing to psoriasis." (PMID 38704587, 2024). "Despite the significance of IL-1β in the pathogenesis of psoriasis, the mechanisms underlying IL-1β dysregulation and rational therapeutic modulation in psoriasis remain to be elucidated." (PMID 38704587, 2024). "Our results suggest that autophagy dysfunction in myeloid cells, especially macrophages, along with IL-1β dysregulation has a causal role in neutrophilic inflammation and psoriasis pathogenesis." (PMID 38704587, 2024). "Regarding inflammatory markers, a low-calorie KD in 30 patients with psoriasis led to decreased IL-1β and IL-2 levels, along with 10% weight loss and 50% reduction in the PASI score." (PMID 38473723, 2024). "To this end, we first examined the localization of IL-1β in association with surface markers for macrophages and neutrophils in the ears of psoriasis-induced mice." (PMID 38704587, 2024). "NLPR1 inflammasome has been implied in prompting the onset of psoriasis, either by increasing the susceptibility to psoriasis or by dysregulated release of pro-inflammatory cytokines including IL-1β and IL-18." (PMID 38347543, 2024).
psoriasis (continued). "For instance, genetic variations of the NLRP1 and NLRP3 inflammasomes have been associated with high levels of IL-1β in the lesions of patients suffering from psoriasis, vitiligo, and atopic dermatitis." (PMID 38068996, 2023). "The pro-inflammatory mediators associated with psoriasis are IL1B, IL2, IL6, IL12, IL15, IL17, IL18, and IL20." (PMID 37569685, 2023). "In psoriasis, IL-1β is mediated by an apoptosis-associated speck-like protein containing a caspase recruitment domain, such as NLRP3 and AIM2." (PMID 37465147, 2023). "It is well established that cytokines TNF‐α, IL‐1β, IL‐6, and IL‐17 are involved in tissue inflammation, especially in skin inflammation associated with psoriasis, and can interact with immune cells to exert proinflammatory effects." (PMID 37506136, 2023). "Accordingly, genes associated with psoriasis, including S100a8, S100a9, Camp, Tnf, Il1b, Il23a, and Ccl2, were strongly downregulated." (PMID 35869084, 2022). "Given that chronic inflammation is a hallmark of psoriasis, we then perform an RT-PCR assay to determine the mRNA levels of IL-1β, IL-6, and TNF-α." (PMID 35351863, 2022). "As the mechanisms, Il-17 and IL-1β, seem to be associated with the development of hypothyroidism in patients with psoriasis, the frequency of Th17 cells in peripheral blood was significantly increased in patients with Hashimoto’s disease." (PMID 35457278, 2022). "In turn, psoriasis-associated inflammatory markers, such as IL-1b, hBD2 and S100A9, were significantly upregulated in the psoriatic skin model at both mRNA and protein levels." (PMID 35745784, 2022). "Genetic studies have shown that IL-1β gene polymorphism can be used to distinguish early-onset and late-onset psoriasis." (PMID 35693833, 2022). "On the other hand, IL1B rs1143623 was associated with Alzheimer’s disease pathology and response to biological treatment in psoriasis." (PMID 33445495, 2021). "Monocytes stimulated by LPCs can produce IL-1β to further activate T lymphocytes to secrete IL-17A, which is an important pathogenic factor in psoriasis." (PMID 33602246, 2021). "Systemic inflammation plays an important role in the pathogenesis of psoriasis, and numerous inflammatory mediators have been implicated, including interleukins (e.g., IL-17, IL-1β), other cytokines and chemokines, and serum autoantibodies." (PMID 34565327, 2021). "We also determined mRNA expression levels of IL-1β, IL-17, and IL-23, all of which are major cytokines associated with psoriasis, by semi-quantitative PCR analysis." (PMID 32707926, 2020). "In psoriasis, IL-1β maturation is mediated by ASC (Apoptosis-associated speck-like protein containing a caspase recruitment domain) -dependent inflammasome complexes, such as NLRP3 and AIM2, which activate caspase-1." (PMID 30744173, 2019). "At baseline, psoriasis patients had higher salivary levels of IL-1β, evaluated via an enzyme-linked immunosorbent assay (ELISA), in comparison to healthy individuals." (PMID 29888276, 2018). "In psoriasis, caspase-1 is active in epidermal keratinocytes and has been linked to IL-1β production via ASC-dependent inflammasome complexes, such as NLRP3 and AIM2." (PMID 28422993, 2017). "In human skin cultures, chemerin is significantly downregulated by IL-17 and IL-22, key cytokines implicated in psoriasis, whereas it is upregulated by acute phase cytokines oncostatin M and IL-1β." (PMID 25659101, 2015). "In order to explore the relationship between PGGT1B deficiency and inflammation in psoriasis, we measured the mRNA and cytokine expressions of inflammatory factors IL-1β, IL-6, TNF-α, IL-17A, and IL-10 in the most serious stage of skin injury in mice using Luminex and qRT-PCR." (PMID 40430037, 2025). "Additionally, the intensity of psoriasis and the success of treatment are linked to the protein levels of IL-1β in the affected skin." (PMID 40343299, 2025).
psoriasis (continued). "In this study, in order to explore the relationship between PGGT1B deficiency and inflammation in psoriasis, we also detected the mRNA and cytokine expressions of inflammatory factors IL-1β, IL-6, TNF-α, IL-17A, and IL-10 in the most serious stage of skin injury in mice." (PMID 40430037, 2025). "WY14643 treatment significantly downregulated psoriasis‐associated inflammatory cytokines and chemokines (Il17a, Il1b, Cxcl1, Cxcl2, Cxcl3, Cxcl15, and Csf3) as well as the antimicrobial peptides S100a8 and S100a9 in IMQ‐induced skin lesions at the transcriptional level." (PMID 40878384, 2025). "The results revealed that autophagy deficiency in myeloid cells is causally linked to IL-1β dysregulation and neutrophilic inflammation in a murine model of psoriasis, which was supported by the analysis of gene expression profiles in psoriatic skin lesions from patients." (PMID 38704587, 2024). "Thus, to probe the pathogenic role of IL-1β dysregulation in psoriasis, we assessed the effect of IL-1 blockade on psoriatic skin inflammation linked to autophagy deficiency." (PMID 38704587, 2024). "Collectively, our findings suggest that IL-1β dysregulation in autophagy-deficient myeloid cells, particularly macrophages, is a potential mechanism underlying aggravated neutrophilic inflammation in psoriasis." (PMID 38704587, 2024). "Furthermore, a genetic study has shown an association between IL1B polymorphisms and late onset of psoriasis." (PMID 38704587, 2024). "IL‐17 and IL‐1β, which are implicated in psoriasis pathogenesis, are also known to downregulate keratinocyte adhesion proteins, at least partially explaining the dysregulation of the TJ function in psoriasis." (PMID 36919255, 2023). "We examined whether the key cytokines (TNFα, IL-22, IL-1β, IL-17A) implicated in the pathogenesis of psoriasis modulate the circadian oscillation of the clock genes in HaCaT keratinocytes." (PMID 35008548, 2021). "We further integrate these findings with those from GWA studies to assess whether IL-1B and IL-36 target genes are genetically associated with psoriasis or other autoimmune conditions." (PMID 29434599, 2018). "So far, caspase-1 has been identified active and linked to IL-1β maturation in psoriasis." (PMID 28422993, 2017). "Because our EC data and previous studies have demonstrated that IL-1α and IL-1β contribute to vascular inflammation/atherogenesis, the elevated activity of IL-1 in psoriasis may contribute to this increased risk of atherosclerosis." (PMID 28323859, 2017). "Additionally, psoriasin is a chemotactic for CD4+ T cells and neutrophils, and is induced by psoriasis-associated inflammatory cytokines that include IL-1β, IL-17, IL-22, and TNF-α." (PMID 28360856, 2017). "Moreover, mice with keratinocyte‐specific Fads2 knockdown exhibited increased mRNA levels of psoriasis‐associated inflammatory mediators, including Il17a, Il1b, and Cxcl1, in both the dorsal and ear skin, and greater neutrophil infiltration was confirmed by flow cytometry." (PMID 40878384, 2025). "However, the mechanism underlying IL-1β dysregulation in psoriasis pathogenesis is unclear." (PMID 38704587, 2024). "Furthermore, IL-1R1 blockade was found to alleviate psoriatic skin inflammation, decrease Cxcl2 expression, and diminish neutrophilia, suggesting that IL-1β dysregulation due to autophagy deficiency plays an important role in psoriasis pathogenesis by driving neutrophilic inflammation." (PMID 38704587, 2024). "Nevertheless, the role of the AMPK pathway in psoriasis remains understudied, and the regulatory mechanisms linking IL-1β and AMPK are yet to be elucidated." (PMID 41508030, 2026). "Across all conditions, migration of inserted T cells towards the epidermis and the secretion of psoriasis-associated cytokines (IFN-γ, IL-17, TNF-α, IL-1β, CCL20, IL-6, and IL-10) was observed." (PMID 42039187, 2026).